DOT1L (DOT1 like histone lysine methyltransferase)
Diseases named in the same sentence as DOT1L in open-access papers (continued):
Sharing a sentence is not in itself a finding about the gene and the disease.
heart failure (1 paper, 2022). Inability of the heart to pump blood at an adequate rate to meet tissue metabolic requirements. "Thus, we proposed that myocardial Ang II signaling leads to upregulation of the Dot1L to facilitate differentiation from cardiac fibroblasts into collagen-producing myofibroblasts, which is vital to development of myocardial fibrosis and heart failure." (PMID 35986422, 2022). "In this study, we demonstrated that Dot1L could be a novel myofibroblasts activator, which upregulation in a mouse model of MI is an accomplice in myocardial fibrosis and consequent heart failure via FoxO3a-induced fibroblast activation and differentiation into collagen-producing myofibroblasts." (PMID 35986422, 2022).
hemorrhage (1 paper, 2024). Loss of blood from the vascular compartment to the exterior or into nonvascular body space as a result of rupture or severance of the blood vessels. "Consequently, it is plausible that the cerebrovascular hemorrhage observed in the induced DOT1L KO mice was due to the repressed expression of these cell-cell adhesion molecules." (PMID 38665093, 2024).
joint disease (1 paper, 2017). "Mechanistically, the protective function of DOT1L is attributable to inhibition of Wnt signalling, a pathway that when hyper-activated can lead to joint disease." (PMID 28627522, 2017).
keratitis (1 paper, 2021). A corneal disease that is characterized by inflammation of the cornea. "In vitro and in vivo models were assessed to investigate the role of Dot1l in HSV-1 induced keratitis." (PMID 33628364, 2021).
kidney damage (1 paper, 2012). "Nevertheless, further studies using animal models deficient in Dot1l, Af9, and Edn-1 are required to conclusively demonstrate the role of these players in the spironolactone-mediated improvement of kidney damage in STZ-induced diabetic animals." (PMID 23077601, 2012).
lymphatic disorders (1 paper, 2020). "Furthermore, our results suggest DOT1L as a candidate biomarker for genetic screening to identify the cause of idiopathic lymphatic disorders including chylous ascites and lymphedema." (PMID 31908356, 2020).
lymphoid tumors (1 paper, 2024). "DOT1L expression was higher in hematopoietic and lymphoid tumors than in normal tissues." (PMID 39307938, 2024).
Meniere disease (1 paper, 2023). A disease of the inner ear (labyrinth) that is characterized by fluctuating sensorineural hearing loss; tinnitus; episodic vertigo; and aural fullness. "Our results indicate that Dot1l may be a crucial factor for endolymph regulation and pathogenesis of Meniere’s disease." (PMID 36639782, 2023). "Dot1l may be closely related to endolymph regulation by aldosterone and to pathogenesis of Meniere’s disease." (PMID 36639782, 2023).
mycosis fungoides (1 paper, 2022). Classical mycosis fungoides is the most common type of mycosis fungoides (MF), a form of cutaneous T-cell lymphoma, and is characterized by slow progression from patches to more infiltrated plaques and eventually to tumors. "However, the observation of fusion proteins involving DOT1L in mycosis fungoides suggests that there might be specific CTCL subtypes that are sensitive to DOT1L inhibitors." (PMID 36425063, 2022).
Myocardial fibrosis (1 paper, 2022). "We next investigated the underlying mechanism by which Dot1L promotes myocardial fibrosis." (PMID 35986422, 2022). "In this study, we provided evidence that increased levels of Dot1L contributes to MI-induced myocardial fibrosis and dysfunction in mice." (PMID 35986422, 2022).
myocardial ischemia (1 paper, 2022). A disorder of cardiac function caused by insufficient blood flow to the muscle tissue of the heart. "Consistently, in vivo Dot1L ablation rescued myocardial ischemia-induced cardiac fibrosis and improved cardiac function." (PMID 35986422, 2022).
oral cancer (1 paper, 2025). "For example, the deregulation of HIF-1-dependent expression of genes like MMP1, MMP2, TWIST, VIM, and CDH1 in oral cancer is linked to the interaction of DOT1L proteins with MLLT3." (PMID 39991574, 2025).
Polyuria (1 paper, 2013). An increased rate of urine production. "Mice with Dot1l deficiency in renal Aqp2-expressing cells (Dot1lAC) develop polyuria by unknown mechanisms." (PMID 23326416, 2013). "In this report, we uncover a new mechanism by which Dot1l regulates water homeostasis, and identify Aqp5 as a potential novel target of Dot1a, a binding partner of Aqp2, a negative trafficking regulator of Aqp2, and thus the potential missing component linking disrupted Dot1l to polyuria." (PMID 23326416, 2013).
postmenopausal osteoporosis (1 paper, 2018). Metabolic disorder associated with fractures of the femoral neck, vertebrae, and distal forearm. "The relationship between DOT1L expression levels in bone tissue or serum and postmenopausal osteoporosis (OP) requires further investigation." (PMID 29348610, 2018).
progeria (1 paper, 2020). "In addition, pharmacological inhibition of DOT1L in a progeria mouse model partially rescued the abnormal osseous phenotype." (PMID 32083237, 2020).
pulmonary disease (1 paper, 2024). "Recently, it was also reported that DOT1L inhibition exerted the anti-fibrosis effect in pulmonary disease through the inactivation of lung fibroblast." (PMID 38172378, 2024).
sarcopenia (1 paper, 2024). Progressive decline in muscle mass due to aging which results in decreased functional capacity of muscles. "Research has shown that histone methyltransferase DOT1L expression is reduced in the vastus lateralis muscle of COPD individuals with sarcopenia, and in vitro DOT1L knockdown significantly upregulates p21 expression." (PMID 39125931, 2024).
spina bifida (1 paper, 2020). A congenital neural tube defect in which vertebrae are not fully formed. "We focused our analyses on E12.5, where we observed highest levels of DOT1L expression, and on the lumbar spinal cord, where NTD like spina bifida are observable." (PMID 32471461, 2020). "Moreover, a direct link that DOT1L might be necessary for proper spinal cord development was suggested through observation that lack of H3K79 dimethylation, mediated by DOT1L activity, occurred at higher frequency in human fetuses presenting with spina bifida." (PMID 32471461, 2020).
cancer (107 papers, 2010 to 2026). A tumor composed of atypical neoplastic, often pleomorphic cells that invade other tissues. "Dot1L functions by catalyzing histone H3 mono-, di- and tri-methylation on lysine-79 and has been linked to several cellular and molecular processes in cancer." (PMID 35850772, 2022). "Initially, DOT1L was associated with cancer progression following the discovery of its crucial role in the development of mixed lineage leukemia (MLL), where the activity of this enzyme has been extensively studied for the last 20 years." (PMID 35495127, 2022). "Having shown that down-regulated DOT1L(K358) acetylation is associated with a decrease in cancer-cell migration and invasion in vitro, we determined the effects of DOT1L(K358R) on CRC metastasis in vivo using a bioluminescence imaging approach." (PMID 32042335, 2020). "In cancer, oncogenic fusion proteins caused by chromosomal rearrangements have been linked to DOT1L-mediated leukemogenesis." (PMID 25561745, 2015). "Oncogenic activation of DOT1L has been implicated in several cancers." (PMID 38495505, 2024). "For instance, high expression of DOT1L may be associated with poor prognosis in HCC patients by mining public cancer databases." (PMID 37171044, 2023). "In undifferentiated pleomorphic bone sarcoma and in adrenocorticotropic hormone–independent macronodular adrenocortical hyperplasias DOT1L recurrent mutations were identified, highlighting the potential role of deregulated chromatin remodeling pathways also in these cancer types." (PMID 35495127, 2022). "Furthermore, we provide the clinicaland in vivo evidence that DOT1L is associated with aggressive phenotypes ofbreast cancer." (PMID 26199140, 2015). "Therefore, it has been proposed that the loss/degradation of DOT1L could be beneficial for cancer therapeutics." (PMID 35331314, 2022). "Zhang X showed that miR-133b reduced cancer cell stemness and decreased chemoresistance to treatments like 5-fluorouracil by inhibiting DOT1L." (PMID 40871106, 2025). "DOT1L, as a pivotal epigenetic factor regulating cancer stemness, is an emerging therapeutic target for various cancers." (PMID 41533929, 2025). "DOT1L was also shown to be a cancer stem cell (CSC) regulator in triple-negative breast cancer (TNBC), and its inhibition suppressed in vivo tumor growth and metastasis by decreasing TNBC CSCs." (PMID 41299712, 2025). "The involvement of DOT1L in multiple cancer processes provides compelling support for its inhibition as a basis for targeted therapeutics against cancers." (PMID 38225241, 2024). "Consistent with this, the expression of an acetylation mimetic mutant of DOT1L was found to induce a cancer-like phenotype in vitro, further emphasizing the role of DOT1L acetylation in CRC progression." (PMID 39394462, 2024). "Given that tumor metastasis is positively or negatively mediated by lymphatics, the identified genes regulated by Dot1l can be targets for the detection or prevention of cancer progression." (PMID 37397258, 2023). "Protein–protein interactions between the most frequent MLL fusion partner proteins AF9/ENL and AF4 or histone methyltransferase DOT1L are critical to malignant gene expression and are therefore a potential drug target for cancer." (PMID 37958457, 2023). "In contrast to DOT1L inhibitors which are targeted, bortezomib has pleomorphic effects on cancer cells that likely also contribute to the activity seen in our studies." (PMID 36781850, 2023). "Given the potential clinical relevance of targeted DOT1L activity in various cancer therapies, identification of the precise molecular mechanisms of the methyltransferase independent DOT1L function in the regulation of gene expression is a priority." (PMID 35401699, 2022). "Evaluation of therapeutic potential of DOT1L pharmacological inhibition has proved to be effective in treatment of multiple cancer types including ovarian, breast, prostate and other solid tumours." (PMID 36333801, 2022).
cancer (continued). "DOT1L activity in cancer cells is controlled at multiple levels starting from the regulation of the methyltransferase expression to context-dependent modulation of its enzymatic performance." (PMID 35495127, 2022). "DOT1L catalyzes lysine 79 methylation in H3 histone and is essential in many aspects of cancer cell biology, including genome integrity." (PMID 35495127, 2022). "DOT1L is the only lysine methyltransferase that does not contain a SET domain, which is a feature that allowed the development of selective DOT1L inhibitors that are currently investigated in Phase I clinical trials for cancer treatment." (PMID 35495127, 2022). "The potential of Dot1L pharmacological blockade for therapy has been demonstrated also in ovarian, prostate and other cancers." (PMID 35850772, 2022). "Another study, however, reported that DOT1L increases CRC tumorigenic potential by enhancing cancer stemness programs." (PMID 35495127, 2022). "A link between H3K79me and DNA resection during HR repair is established and thus, knockdown of DOT1L increases the sensitivity of cancer cells to irradiation and PARP inhibitors." (PMID 33498525, 2021). "Overall, DOT1L inhibition as a mono or combination therapy holds promise to overcome DNA repair “addiction” and/or cancer stemness." (PMID 33498525, 2021). "SGC0946 has subsequently been employed in a variety of settings to further elucidate the role of DOT1L in cancer and the mechanism of MLL fusion target gene expression." (PMID 34458810, 2021). "Human methyltransferases, such EZH2, PRMT5, and DOT1L, are being actively pursued as drug targets for various cancers." (PMID 34285249, 2021). "Targeting DOT1L deacetylation signaling is a potential therapeutic strategy for DOT1L-driven cancers." (PMID 32042335, 2020). "The therapeutic potential of CBP specific inhibitors has been reported 71, 72; here, our finding further highlights the prospect of CBP inhibitors in cancer therapy, especially in cancers highly expressing DOT1L/CBP." (PMID 32042335, 2020). "Mutating the DOT1L K358 site to R358 renders DOT1L susceptible to degradation via an interaction with the E3 ligase RNF8 and this process inhibits cancer-cell metastasis." (PMID 32042335, 2020). "To further develop novel epigenetic regulators for intractable cancers, we revealed that PsA-3091, a tertiary butyl substituted heteromonomeric disulfide structured analog, showed DOT1L-dependent antitumor activity towards TNBC cells." (PMID 33379275, 2020). "Collectively, these experiments indicate that DOT1L acetylation correlates with cancer-cell migration, invasion and metastasis in vivo." (PMID 32042335, 2020). "Inhibition of DOT1L activity with selective inhibitors resulted in cell growth arrest and massive deregulation of cancer-related genomic pathways, including the ERα gene itself and genes involved in cell proliferation, DNA repair, and drug metabolism." (PMID 31689915, 2019). "Our findings provide a rationale for developing therapeutic agents targeting C/EBPβ or the C/EBPβ-DOT1L interaction, and highlight the importance of identifying chromatin-modifying TFs in cancer." (PMID 29712898, 2018). "DOT1L knockdown blocked the expression of DOT1L, miR-10b, RhoGTPase and survival protein, and reduced cancer invasion and chemoresistance in CSCs." (PMID 28938696, 2017). "In this review, we describe those enzymes and their inhibitors that have already reached the first stages of clinical trials in cancer therapy, namely the histone methyltransferases DOT1L and EZH2 as well as the demethylase LSD1." (PMID 27222667, 2016). "Dot1l, as a methyltransferase for histone H3K79 methylation, was found associations with several cancers." (PMID 27713173, 2016). "Here the authors show that DOT1L expression isassociated with poor survival and aggressive cancers by helping to epigeneticallyactivate the epithelial-mesenchymal transition during breast cancerprogression." (PMID 26199140, 2015).
cancer (continued). "Previously, H3K79 methylation (regulated by DOT1L) was identified as a novel histone marker for ageing and cancer." (PMID 26694192, 2015). "Collectively, we suggest that cooperative effectof DOT1L and c-Myc-p300 is critical for acquisition of aggressive phenotype ofbreast cancer by promoting EMT/CSC." (PMID 26199140, 2015). "First, DOT1L is an enzyme and, thus, can be targeted by pharmacological agents, with DOT1L inhibitors already being tested in cancer clinical trials." (PMID 25561745, 2015). "Our clinical data show theassociation of high DOT1L expression with invasion and metastasis of human breastcancers, as well as the poorer survival rate in an aggressive subset of ER-negativebreast cancers." (PMID 26199140, 2015). "The discovery of novel enzymatic activities that are essential and dedicated to Wnt target gene activation, such as DOT1L, presents potential new targets for rational drug development for the treatment of cancer." (PMID 21103407, 2010). "The histone methyltransferase DOT1L, the sole enzyme catalyzing H3K79 methylation, is increasingly implicated in cancer progression, yet its role in shaping the tumor immune microenvironment (TME) remains unclear." (PMID 41836439, 2026). "Notably, DOT1L is highly expressed and plays a vital role in the malignant progression of a variety of cancers, including OC." (PMID 38778348, 2024). "Since PARPi has been used to treat cancer patients, this newly identified activity raises the question of whether PARPi-induced DOT1L activity increases tumor progression and drug resistance, which could attenuate the therapeutic efficacy of PARPi." (PMID 38778348, 2024). "While the role of DOT1L in cancer and chemoresistance is acknowledged, its specific role in PARPi resistance remains unclear." (PMID 38778348, 2024). "Recent research showed that extracellular glucose could induce DOT1L abundance through O-GlcNAcylating DOT1L and increasing DOT1L stability in cancer cells." (PMID 38172378, 2024). "Apparent contrasting evidences were reported concerning DOT1L involvement in the regulation of the Wnt signaling pathway, known to play a crucial role in stemness maintenance and cell proliferation and to be deregulated in cancer." (PMID 35495127, 2022). "Indeed, according to the literature, DOT1L knock-down has a minimal effect on cancer cell growth, while it plays an essential role during development and embryogenesis." (PMID 34500733, 2021). "Because massive re-replication can drive cell death specifically in checkpoint-compromised cancer cells, both CDT1 stabilization by inactivation of ubiquitin-mediated degradation and inhibition of DOT1L are currently being explored as novel anti-cancer therapeutic strategies." (PMID 34103496, 2021). "DOT1L was previously reported to be overexpressed in several cancer types." (PMID 34253709, 2021). "Until now, Dot1l has been widely studied for cancer pathogenesis and development, however, the role and function of Dot1l in HSK still remain unknown." (PMID 33628364, 2021). "Moreover, in patients with cancers of intermediate grade (Gleason 7), high DOT1L expression was still able to significantly predict poor disease-free survival." (PMID 32814769, 2020). "In summary, our discovery indicates a novel opportunity for DOT1L inhibitors in cancer treatment." (PMID 32215184, 2020). "Accumulating evidence suggests that the inhibition of DOT1L-mediated processes may also suppress the metastasis of human cancer cells." (PMID 32244385, 2020). "The result showed that DOT1L was highly expressed in CRC compared with other 15 types of cancers." (PMID 31888761, 2019). "The development and availability of small molecule inhibitors of DOT1L may provide new and unique therapeutic options for certain types or subgroups of cancer." (PMID 30616689, 2019).